CD4 (CD4 molecule)
Diseases named in the same sentence as CD4 in open-access papers (continued):
Sharing a sentence is not in itself a finding about the gene and the disease.
Sepsis (continued). "We first validated relevance of our CyTOF results by highlighting established immune hallmarks of sepsis, such as decreased monocyte HLA-DR expression and increased expressions of PD1 and PD-L1 on CD4 T cells and monocytes." (PMID 30470767, 2018). "Results indicate that CXCR4 is selectively upregulated on naïve CD4+ and CD8+ T cells and CD4+ central memory T cells following the induction of sepsis, and that CXCR4 antagonism resulted in a significant decrease in sepsis-induced mortality." (PMID 29232699, 2017). "In this series of investigations, we found that CXCR4 blockade improved survival in murine polymicrobial sepsis, increased the absolute number of circulating CD4+ and CD8+ T cells, and mitigated sepsis-induced T cell exhaustion phenotypes." (PMID 29232699, 2017). "Our study shows that CXCR4 is upregulated on naïve CD4+ and CD8+ T cells, as well as CD4+ TCM, during sepsis." (PMID 29232699, 2017). "The aim of this study was to assess the persistence of sepsis-induced immunosuppression at the cellular level at ICU discharge and 6 months thereafter by measuring mHLA-DR, CD4+ T cells, and Treg expression in patients admitted for septic shock." (PMID 28770544, 2017). "Our findings revealed that T. gondii infection robustly induces long-lived IFN-γ- and TNF-α-producing CD4+ and CD8+ T cells that are maintained, reprogrammed and amplified to act against a secondary challenge of sepsis." (PMID 28439500, 2017). "We probed the mechanistic basis for these findings and found that CXCR4 antagonism significantly increased the number of peripheral CD4+ and CD8+ T cells following sepsis." (PMID 29232699, 2017). "The PD-1 levels were increased in peripheral blood CD4+ T cells and CD8+ T cells of both T2DM patients and those with severe sepsis, suggesting that both diseases involve immune suppression." (PMID 27459386, 2016). "In this study, we interrogated the impact of chronic alcohol exposure on activation and effector function of CD4+ and CD8+ T cells following sepsis." (PMID 27861506, 2016). "Within CD44hi memory CD4+ T cells, a distinct CD69+CD43+ population was identified in the setting of sepsis." (PMID 27861506, 2016). "The ratios of CD4+ T cell: CD8+ T cell are relatively lower in patients with sepsis, compared to non-sepsis patients." (PMID 27556404, 2016). "Nevertheless, the impact of sepsis on the serum concentration of tuftsin and the expression of Nrp-1 on CD4+CD25+Tregs, as well as the potential therapeutic value and mechanisms of tuftsin in sepsis remains to be elucidated." (PMID 27835904, 2016). "In this study, our results also highlighted the contribution of T regs expansion to the development of immunosuppression, and identified the roles of T regs in regulating the numbers and activities of CD4+, CD8+ T cells and NK cells in sepsis." (PMID 26918357, 2016). "In the total CD4+ population, CD69 expression increased significantly 24h after sepsis induction in water fed animals." (PMID 27861506, 2016). "al. observed a reduction in CD4+ and CD8+ T cells in the acute phase and an increase of regulatory T cells in the process of sepsis." (PMID 27056672, 2016). "As highly specialized type of antigen-presenting cell (APC), DC activate CD3+ (total T cells), CD4+ (helper T cells), and CD8+ (cytotoxic T cells), which is considered as important pathway for Tα1 to reverse immune suppression in sepsis." (PMID 27633969, 2016). "There was a stepwise reduction in the percentage of BTLA+/CD4+T cells within 24 h of ED admission in patients with SIRS compared with patients with sepsis, severe sepsis, or septic shock (P <0.01)." (PMID 26329820, 2015). "The area under the receiver operating characteristic (AUC) curves of BTLA expression on CD4+ T cells was slightly lower than that of procalcitonin (PCT) and Mortality in Emergency Department Sepsis (MEDS) score." (PMID 26329820, 2015).
Sepsis (continued). "Results showed that IL-15 administration significantly inhibited the apoptosis of splenic CD4, CD8, NK, and DCs induced by sepsis." (PMID 25821827, 2015). "We focused primarily on the combined effects of pathogen load, phagocytic cells, tissue damage, anti-inflammatory cytokine, CD4+ T cell, CD8+ T cell, B cell, and antibodies by adding cellular pathways during sepsis progression." (PMID 26446682, 2015). "In the early stage of sepsis, there was a stepwise reduction in the percentage of BTLA+/CD4+T cells in patients with SIRS compared with patients with sepsis, severe sepsis, or septic shock." (PMID 26329820, 2015). "HIV-infected patients with sepsis were more likely to have AKI (59%) and 9/13 of the AKI patients who died were HIV positive with a range of CD4 8–361." (PMID 25592556, 2015). "Furthermore, there have been no studies exploring whether BTLA expression on circulating CD4+ T lymphocytes is associated with the mortality of patients with sepsis." (PMID 26329820, 2015). "In peripheral blood, sepsis induced a significant increase of PD-1 and CTLA-4 expression in CD4+ T cells in young and aged mice." (PMID 24962182, 2014). "Our investigation shows that ATP_CD4 may potentially serve as marker to discriminate between patients with better post-AKI outcome (complete renal recovery) from patients with partial recovery of renal function including persistent need for dialysis, and from patients with sepsis-associated death." (PMID 25522739, 2014). "It has been reported that the prognosis of sepsis correlates closely with the numbers of NK cells, CD3+, CD3+CD4+ and CD3+CD8+ lymphocytes." (PMID 24939221, 2014). "Reductions in circulating CD4+ T-lymphocytes and their shift to a TH2 phenotype characterize aspects of sepsis-induced immunosuppression." (PMID 25302303, 2014). "Firstly, we demonstrated that autophagy was down-regulated in CD4+ and CD8+ T cells in the late stage of sepsis." (PMID 25029098, 2014). "We further identified the expression levels of LC3-II and ATG7 by lysate proteins extracted from CD4+ and CD8+ T cells at 24 h after CLP, as autophagy detected by Cyto-ID Green/acridine orange staining was inhibited at the late stage of sepsis." (PMID 25029098, 2014). "Although lymphocyte apoptosis has been reported in sepsis, the observation that there are lower levels of CD3+ and CD4+ lymphocytes in the MTSG is novel." (PMID 24886652, 2014). "We feel that the data presented here concerning BTLA expression on CD4+ T cells in critically ill ICU patients and experimental mice importantly add novel insight as to how ligation of BTLA may contribute to the induction of the adaptive immune cell loss that is associated with sepsis." (PMID 24289156, 2013). "Finally, studies that adoptively transfer BTLA-/- CD4+ T cells into WT mice may be able to elucidate whether BTLA expression on CD4+ T cells inappropriately drives an exhausted form of CD4+ T cells into circulation during experimental sepsis." (PMID 24289156, 2013). "Thus, patients with severe sepsis might benefit from increased CD4+ and CD8+ lymphocytes." (PMID 23670410, 2013). "To address the impact of sepsis on natural Tregs, we subjected DEREG mice to CLP and measured the proportion of Foxp3+ cells in the CD4+ T cell population." (PMID 23724126, 2013). "Lymphocyte apoptosis is increased in CD4+ and CD8+ T cells in sepsis as compared to non-sepsis patients." (PMID 23670410, 2013). "But in a prospective observation study on sepsis in two Ugandan Hospitals, it was found that most patients with bacteraemia were HIV-infected with a median CD4+ count of 52 cells/mm3." (PMID 23075077, 2012). "Patients with blood stream infections, oesophageal candidiasis, and HIV-wasting syndrome had the lowest median CD4 counts (85, 77, and 34 cells/μl, respectively)." (PMID 20126383, 2010).
Sepsis (continued). "A decrease of CD4-lymphocytes of patients with CAP or intraabdominal infections and severe sepsis/shock was found compared with CAP or intraabdominal infections and sepsis." (PMID 20504311, 2010). "A drop in circulating CD3+CD4+ and CD3+CD8+ T cells has been described in patients with severe sepsis or septic shock at admission to the ICU." (PMID 19243622, 2009). "In a study on neonates with documented sepsis, up regulation of CD45RA+RO+ cells on CD4+ cells was detected early in the infection." (PMID 19091070, 2008). "Here we characterized the metabolic properties of human CD4+ T cells from critically ill patients with and without sepsis and healthy adults." (PMID 41540263, 2026). "Furthermore, we observed significantly reduced TCR diversity accompanied by altered CDR3 sequence characteristics and VJ gene usage frequencies in several CD4+ and CD8+ T cell subsets from sepsis patients." (PMID 41853277, 2026). "Although CD4 count and TyG index individually capture critical aspects of immune and metabolic status, little is known about their combined value in predicting short-term mortality among PLWH with sepsis." (PMID 41601726, 2026). "Recently, it was shown that sepsis induces chronic non-specific production of IL-17 by CD4 T cells, resulting in the inability to mount an effective immune response and increasing the susceptibility to secondary infections in sepsis survivals." (PMID 40076848, 2025). "Comparison of inflammatory factors, T lymphocyte subsets and markers on CD4+ T cells between elderly and non-elderly sepsis patients." (PMID 40933998, 2025). "To explorethis, we intraperitoneally (i.p.)injected PICS and sepsis model mice with anti-CD115,anti-B220, and anti-CD25 antibodies to deplete monocytes, B cells, and CD4 Tregs,respectively, and then observed whether there was a change in the number of MKs." (PMID 40443348, 2025). "ERS in CD4+ T cells is enhanced in sepsis patients, particularly in elderly and non-survived individuals." (PMID 40933998, 2025). "ATP11B, upregulated in sepsis, shows a negative correlation with memory B cells and a positive correlation with resting NK cells and activated memory CD4+ T cells, suggesting its role in regulating the transition from hyperinflammation to immunosuppression." (PMID 41394771, 2025). "B- and T-lymphocytes are major components of the immune system, and prior research has shown that neonates with culture-confirmed sepsis had lower absolute counts and CD4+ T-lymphocyte ratios than those without." (PMID 41378197, 2025). "Although the correlations between CD3%, CD4%, and APACHE II scores were weak, they suggest that immune cell percentages may serve as indirect markers of disease severity in sepsis patients." (PMID 40642098, 2025). "The frequencies of conventional CD8 or CD4 T cells or DN non‐MAIT T cells were similar between sepsis patients with positive and negative blood cultures." (PMID 40041474, 2025). "The MFIs of LC3II, P62, CHOP and GRP78 on CD4+ lymphocytes were also higher in the non-surviving sepsis patients (249.9 versus 134.8, P<0.001; 323.7 versus 200.6, P=0.002; 390.8 versus 177.6, P<0.001 and 389.1 versus 227.0, P<0.001)." (PMID 40933998, 2025). "ERS in CD4+ T cells was enhanced in sepsis patients, particularly in elderly and non-survived individuals; ERS is strongly associated with mTOR-mediated autophagic-lysosomal disorder." (PMID 40933998, 2025). "Without stimulation, patients in the sepsis cohort had a lower proportion of CD4+ T cells producing IL-10 than did healthy controls." (PMID 39935482, 2025). "The same resultswere obtained in the sepsis groups,indicating that MKs were not affected by changes in the numbers of B cells and CD4 Tregs." (PMID 40443348, 2025).
Sepsis (continued). "Individually, higher frequency of CD15+CD14+monocytes [0.83 (95%CI 0.71,0.94)], CD45RA-CX3CR1+CTLA4+CD4+ T cells [0.77 (95%CI 0.64,0.90)], CD45RA−17A+CD4+ T cells [0.76 (95% CI 0.61,0.90)], and Ki67+ B cells [0.76 (95%CI 0.64, 0.88)] yielded good AUROC for distinguishing sepsis from healthy." (PMID 40433376, 2025). "The CD4+ T cell count, CD4+CD28+ T cell count, CD8+ T cell count and CD8+CD28+ T cell count were also significantly lower in elderly sepsis patients (194 versus 474, P<0.001; 180 versus 451, P=0.001;107 versus 199, P<0.001; 35 versus 132, P<0.001 respectively)." (PMID 40933998, 2025). "Moreover, flow cytometry analysis of CD4+ T cell subsets demonstrated that LPS stimulation and CLP-induced sepsis resulted in an elevated proportion of T helper 2 (Th2)/Th1 cell subsets." (PMID 40995563, 2025). "Results showed that macrophages, monocytes, neutrophils, natural killer (NK) cells, T helper 17 cells, and dendritic cells were upregulated, and CD8+ T cells, CD4+ T cells, T-regulatory cells, and T follicular helper cells (TFH) were downregulated in the whole blood of patients with sepsis." (PMID 40184094, 2025). "The sepsis cohort, compared to healthy, had a lower proportion of CD4+ T cells producing IL-10 without ex vivo stimulation (p=0.01)." (PMID 39935482, 2025). "The current study reveals significant correlations between the ERS marker-CHOP MFI and autophagic-lysosomal disorder markers-LC3II and P62 MFIs in CD4+ lymphocytes in sepsis patients, particularly in elderly sepsis and non-survived elderly ones." (PMID 40933998, 2025). "During days 1 to 3 (D1-3), the relative expression of miR-146b-5p, CD3%, and CD4% demonstrated negative correlations with the APACHE II scores in sepsis patients (r = -0.224, p = 0.0241; r = -0.280, p = 0.0046; r = -0.240, p = 0.0156)." (PMID 40642098, 2025). "Our study identified significantly elevated expression of MYH9 in CD4+ T cells, CD8+ T cells, and HSC, as well as in monocytes, neutrophils and NK cells, indicating its potential involvement in the immune dysregulation observed in sepsis." (PMID 40861493, 2025). "To test and explore the viability of targeting mTOR to regulate CD4+ T-cell autophagy in sepsis as a way to minimize CTLA4 accumulation and hence alleviate CD4+ T-cell dysfunction, we employed rapamycin, a particular mTOR inhibitor, to corroborate the genetic approach's results." (PMID 39104632, 2024). "Four outcomes were analysed in univariable analysis, of which CD4–5,50 CD1 and CD265 showed an association but sepsis did not." (PMID 39370740, 2024). "A recent study using a mouse model of burn injury and sepsis has shown that Flt3L treatment mitigates T cell depletion, restores CD28 expression on CD4+ and CD8+ T cells, and increases IFN-γ production by CD8+ T cells, thereby reducing organ injury markers and enhancing survival." (PMID 39720718, 2024). "This may be one of the factors related to the prognostic value of M-MDSCs in sepsis, when CD14+ cells (M-MDSCs) were depleted, CD4+ and CD8+ T cells in patients with sepsis proliferated rapidly." (PMID 38609858, 2024). "In our study, based on the overall immune environment in sepsis, we first explored the effect of mTOR regulation of CTLA4 on overall CD4+ T-cell function, and further experiments and discussions are needed in the future on the function of different cell subtypes, such as Treg cells, Th17." (PMID 39104632, 2024). "This suggests that subjects exposed to CD4 Treg AC are approximately 0.08% more likely to develop sepsis compared to those not exposed." (PMID 39465765, 2024). "Area under the curve of CD4+ T lymphocyte counts (0.662 and 0.551–0.774) indicated that it is an effective marker for predicting the short-term mortality of sepsis, although its predictive value was not too high." (PMID 39290582, 2024).
Sepsis (continued). "Additionally, their results indicated that blocking TIM-3 in CD4+ T cells led to the activation of the NF-κB/TNF-α signaling pathway, which counteracted sepsis-induced immunosuppression." (PMID 38576606, 2024). "In the same way, the co-stimulatory molecules PD-1 and exhaustion markers CD39 frequency (respectively, CD3+CD4+CD25+CD127-FOXP3+ cells and CD3+CD4+CD25+CD127-FOXP3+PD-1+), showed an increase in neonates developing sepsis compared to healthy newborn and those with presumed sepsis." (PMID 39072327, 2024). "No causative relationships were observed between sepsis risk and the absolute counts of other lymphocyte subgroups such as CD8+ T cells, CD4+ CD8dim T cells, natural killer T cells, B cells (B cell absolute count), and HLA DR+ natural killer cells." (PMID 39465765, 2024). "The expression of CTLA-4 on CD4+ lymphocytes significantly correlated with LC3II expression in patients with sepsis, patients with SAI, and non-surviving patients with SAI." (PMID 39104530, 2024). "Drawing from two distinct knockout models, namely T-cell-specific TSC1 knockout (TSC1-KO) mice and T-cell-specific mTOR knockout (mTOR-KO) mice, we investigated the mTOR pathway's regulatory function on the autophagy level of CD4+ T cells and CTLA4 accumulation in sepsis." (PMID 39104632, 2024). "A global, post-sepsis state of anergy has been proposed in CD4+ T cells, through evidence of little or no pro- or anti-inflammatory cytokine production evident following anti-CD3/CD28 stimulation in post-mortem spleen and lung samples." (PMID 38197178, 2024). "Patients who did not survive to sepsis had a significantly greater incidence of apoptosis in lymphocytes, particularly CD4+ cells, compared to those who survived." (PMID 38474403, 2024). "For the sepsis group, we observed a statistically significant negative correlation between CD4+ and CD8+ and between CD4+ and NKT on both studied days, suggesting a decrease in the value of both helper and cytotoxic lymphocytes." (PMID 39684323, 2024). "In line with prior researches, our data indicated that DEARGs in sepsis exhibited predominant positive correlations with macrophages, neutrophils, and T cells, while displaying a negative correlation with CD4/CD8 ratio of T cells." (PMID 38281996, 2024). "Consistent with this notion, we found that immune indicators including proinflammatory cells (monocytes, NK cells, DCs, Th1, Th17, and Tfh cells, as well as CD4+ and CD8+ T cells), anti-inflammatory cells (MDSCs, Treg cells, and Th2 cells), and inflammatory cytokines were markedly altered in sepsis." (PMID 38707899, 2024). "Although depletion of CD4 T cells did not affect bacterial clearance during sepsis, the depletion of CD8 T cells lead to increased bacterial burden in the PF and spleen in the KO mice." (PMID 38720893, 2024). "In instances of sepsis, there was an elevated count of monocytes, macrophages, memory B cells, and neutrophils, whereas the healthy control group exhibited a higher number of CD8 T cells, naive CD4 T cells, and resting NK cells." (PMID 39763654, 2024). "Sepsis augments the population of splenic DCs that do not express CD8 and CD4 molecules; however, it induces a substantial loss of CD8- or CD4-expressing splenic DCs." (PMID 38667530, 2024). "In addition, they reduced the number of CD4+, CD8+, and CD3+ T cells in the spleen, which is characteristic of immunosuppression during sepsis." (PMID 38169726, 2024). "In summary, research on murine sepsis models demonstrated the potential therapeutic value of CB2R modulation, with CB2R activation improving survival and mitigating inflammation while revealing complexities in its role within CD4+ T cells." (PMID 38775488, 2024). "The MTF1-T-cell CD4 memory resting cells were the most negatively correlated DECuG–immunocyte pair (r = −0.61, P-value<0.001), with a lower expression level of MTF1 and a lower infiltration of T-cell CD4 memory resting cells in sepsis." (PMID 38495196, 2024).